TLR4 (toll like receptor 4)
Diseases named in the same sentence as TLR4 in open-access papers (continued):
Sharing a sentence is not in itself a finding about the gene and the disease.
infection (continued). "Some literatures show that TLR4 is upregulated when stimulated by M. tb or virulence proteins and subsequently activates a series of signaling pathways and increases pro-inflammatory cytokines expression, and some literatures show that TLR4 is downregulated during infection." (PMID 36992931, 2023). "Together, Xu's and our findings demonstrate that downregulation of Triad3A may be a potent weapon against pathogen infection through activating the autophagy mechanism and TLR4‐NO pathway." (PMID 37506157, 2023). "Furthermore, TLR4-dependent viral entry and infection progression of respiratory syncytial virus (RSV) has been described in mice model." (PMID 37153546, 2023). "TLR4 deficiency did not alter the frequency or number of lung-infiltrating MDSCs post infection, compared to WT controls." (PMID 37524886, 2023). "During an infection or inflammatory disease, S100 proteins exacerbate the inflammatory response by increasing the production of proinflammatory cytokines in immune cells in an autocrine and paracrine manner through the interaction with TLR4." (PMID 38049858, 2023). "Of note, CP can be pro-inflammatory via binding to Toll-like receptor 4 (TLR4) which could impact inflammation, particularly neutrophil recruitment to the site of infection." (PMID 37358277, 2023). "In addition, markers (TLR4, CD68, Tyrobp and Cx3cr1) associated with microglial activation were significantly upregulated post infection." (PMID 38093309, 2023). "The innate immunity induced by TLR4 plays a vital role in fighting against pathogen infection." (PMID 37443803, 2023). "Furthermore, EV71 replication was significantly decreased in human-derived TLR4 and TLR2/TLR4 heterodimer-overexpressing RD cells in an infection-dose-dependent manner." (PMID 37207203, 2023). "While TLR4-mediated inflammatory responses to infection or trauma are intended to protect the host, an overexuberant response may lead to tissue damage." (PMID 37768050, 2023). "However, the total expression of TLR4 was found to increase during infection and TAK-242 (1μM) treatment in comparison to mock, significantly [from 81.5 ± 1.592 (Mock) to 90.73 ± 1.874% (CHIKV) and 89.15 ± 1.084% (TAK-242)]." (PMID 37153546, 2023). "At 3 h post infection the TLR4 level was increased to 253% which increased significantly at 6 h (506%, p < 0.0001), 12 h (716%, p < 0.0001) and reached to the level 823% (p < 0.0001) at 24 h post infection when compared to the level expressed at 0 h post JEV infection." (PMID 36707891, 2023). "Hepcidin production in response to infection may be facilitated by activating the toll-like receptor 4 (TLR4) in macrophages." (PMID 36895478, 2023). "TLR4, belonging to the pattern recognition receptor family of genes, plays an important role in activating the innate immune response, participating in the body's response to infection due to various pathogens." (PMID 36865438, 2023). "Hence, the current study suggests a positive regulation of TLR4 on CHIKV entry, infection and associated inflammation in the host." (PMID 37153546, 2023). "While HylB promoted ascending GBS infection in wild-type (WT) and CD44-deficient mice, surprisingly, mice lacking both TLR2 and TLR4 (TLR2/4) were able to curtail these infections." (PMID 37747229, 2023). "Effects of Tlr4 KO and Ccr2 KO on leptomeningeal EC responses to infection." (PMID 37318981, 2023). "Although TLR4 is not required for IRE1α activation during B. abortus infection, TLR4-deficient macrophages show a reduction in glycolytic flux during infection, suggesting that TLR4 can support glycolysis via IRE1α-dependent and IRE1α-independent mechanisms." (PMID 36475773, 2023). "TLR4 coreceptor CD14 mRNA expression faithfully copied TLR4 mRNA expression and showed upregulated expression after infection with Salmonella without any influence of previous association with commensal bacteria." (PMID 38003758, 2023).
infection (continued). "So, the focus was on the association of SCARB1 receptor with TLR4 signalling pathways in infection in dairy ruminants, which has not been highlighted earlier as most studies have focused on the role of SCARB1 as a lipoprotein receptor." (PMID 36604713, 2023). "Platelets are known responders to infection through the TLR4/CD14 immune complex." (PMID 37222974, 2023). "TLR4 is a TLR family member critical for innate immune response to infection." (PMID 37122744, 2023). "Meanwhile, the TLR4 expression level is closely related to pathogen infection." (PMID 37443803, 2023). "Notably, the bacterial ligand Pam3CSK4 (TLR1/2) and LPS (TLR4) specifically increased the infection levels in vaginal immature LCs." (PMID 36841916, 2023). "Moreover, this LDs and FOXO3-mediated immune sensitivity to infection is shown in FOXO3 KO colon with increased bacterial LPS sensing TLR4." (PMID 37298680, 2023). "Overall we noticed an increase in TLR4 level with increasing time points post infection." (PMID 36707891, 2023). "TLR-2 has been shown to be important for late stages of infection when compared to TLR-4." (PMID 36121578, 2022). "It was shown that TLR4-deficient nonpregnant mice were highly susceptible and succumbed to the infection; hence, this innate receptor would play a critical role in appropriate sensing the parasite with subsequent induction of immune responses." (PMID 35722460, 2022). "In addition, lipid A, which is present in both the virulent Nine Mile isolate and the attenuated NMII, has been shown to inactivate TLR4-dependent host responses to infection." (PMID 35913176, 2022). "To mimic such a state, we first treated MDMs with either 10 ng/mL or 100 ng/mL of the Toll-like receptor 4 (TLR-4) ligand lipopolysaccharide (LPS) for 24 h prior to infection; in parallel, we treated other wells of MDMs with either 10 ng/mL or 100 ng/mL of IFN-α." (PMID 35975998, 2022). "In addition, a study on the MG-Rlow strain showed that MG-Rlow infection upregulated HMGB1 expression and activated the TLR4 signaling pathway, causing severe lung injury and intestinal flora imbalance in chickens." (PMID 36139393, 2022). "The presence of 5 μg/mL OMVs during MNV infection of macrophages was predicted to induce TLR4." (PMID 35990695, 2022). "The TLR4 expression was very discrete at the same post-infection times." (PMID 35628694, 2022). "The up-regulatory effect on MyD88 and TRIF may be the result of direct viral interaction or the up-regulation effect on cell-membrane- (TLR2 and TLR4) and endosomal-associated (TLR3, TLR8, and TLR9) TLRs induced by single-PDCoV infection." (PMID 36376395, 2022). "However, the capability of the Toll-like Receptor (TLR)-4 agonist lipopolysaccharide (LPS) to protect against subsequent infection was described as early as the 1950s." (PMID 36439136, 2022). "In addition, the overactivation of TLR4 leads to prolonged or excessive innate immune responses after infection with SARS-CoV-2." (PMID 36555339, 2022). "These genes included key components involved in TLR4 inflammatory responses to infection, such as KLF4, for which the context-specific eQTLs link differential enhancer activity and/or chromatin accessibility that were positively correlated with mRNA levels upon LPS treatments." (PMID 35751107, 2022). "Importantly, the presence of either mouse or human TLR4 has been shown to be sufficient to control infection by Leptospira." (PMID 35923802, 2022). "Thus, the activation of the TLR4 pathway appears to serve as a protective means to prevent infection, through its upregulation of inflammatory pathways." (PMID 36499260, 2022). "Meanwhile, TLR4 is involved in immune response during S. aureus-induced infection." (PMID 35762728, 2022).
infection (continued). "Nevertheless, in line with the participation of type I interferons in infections with L. infantum, the analysis of the transcriptional profile of VL patients, combined with the mouse model, provided evidence for a TLR4-IFN-β pathway in the induction of asymptomatic disease." (PMID 35154115, 2022). "We also demonstrated that the positive influence of NE on macrophage infections requires TLR4." (PMID 35154115, 2022). "Previous studies from our group found that the infection with P. gingivalis increases toll-like receptor 4 (TLR4) mRNA levels, and this increase may relate to some changes in cellular events, like apoptosis." (PMID 35978839, 2022). "In our infection model, up-regulated Tlr-4 might have activated these pathways to eventually lead to the expressions of proinflammatory cytokiness such as CXCL1, CXCL2, etc." (PMID 36140754, 2022). "TLR4 signalling, following Mollicutes infections, is poorly described." (PMID 36296238, 2022). "ST infection also showed an increased trend for TLR4 (P = 0.099) and TNF-α (P = 0.096) mRNA levels." (PMID 36221113, 2022). "Three studies analyzed systemic immune responses using stimulation of whole blood or PBMCs with LPS, a Toll-like receptor 4 agonist with an important role in regulation of immune responses to infection, or phorbol 12-myristate 13-acetate (PMA) and ionomycin to induce cytokine responses in T cells." (PMID 36555983, 2022). "Second, we determined the inhibitory activity of the TLR4 antibody using TMUV SRIP infection model." (PMID 36379254, 2022). "Toll-like receptor (TLR)-4 agonists have been shown to trigger host resistance to infection that lasts for up to two weeks in several clinically relevant models of infection, which our group has revealed to be driven by long-term changes in innate immune function supported by metabolic rewiring." (PMID 36439136, 2022). "The TLR4-NF-kB interaction plays a crucial role in initiating infection-induced lung injury." (PMID 36201406, 2022). "Infection experiments were performed using homozygous C57BL/6J-derived MyD88 (-/-) knock-out (MyD88 KO) mice deficient in signaling of all TLRs through the MyD88 adaptor and retaining only the TRIF-mediated endosomal TLR4 and TLR3 signaling pathways." (PMID 35395059, 2022). "In addition, since during infections cell death and tissue damage favor TLR4 activation, we also mimicked TLR4 activation in monocytes through LPS stimulation." (PMID 35592335, 2022). "While other TLRs have been implicated in a variety of infections, not much is known about TLRs, aside from TLR4, in the context of filovirus infections." (PMID 36558734, 2022). "It was shown that TLR2 and TLR4 colocalize with MTs in dendritic cells and the disruption of MTs leads to reduced cytokine production upon infection, suggesting these TLRs are transported in an MT-dependent manner during infection." (PMID 35632720, 2022). "Theoretically, inhibition of TACE could restrict the distribution of GP in the host, limit the TLR4 activation to the site of infection, and significantly reduce cytokine and chemokine activation." (PMID 36288690, 2022). "Moreover, studies have demonstrated increased expression of PTX3 in TLR4-dependent manner and it exhibits opsonizing activity via TLR4 pathway during infection." (PMID 36741398, 2022). "TLR4 is a key component of innate and adaptive immune responses during infection and inflammation." (PMID 35858908, 2022). "To investigate whether ACE2‐mediated internalization of SARS‐CoV‐2 triggers endosomal TLR4, we blocked TLR4 upon infection." (PMID 35099061, 2022). "The expression of TRIM7 in PBMCs of individuals with infection is closely related to its biological role in affecting inflammatory response through regulating the TLR4 pathway, and its change trend is consistent with the results of our previous cell experiments." (PMID 36402943, 2022).
infection (continued). "In this study, the TLR4 gene expression in THP-1 cells in response to the infections produced by different Aeromonas strains of A. media, A. piscicola, and A. jandaei was shown to be upregulated, but the expression was not significantly higher than in the non-infected cells." (PMID 35874671, 2022). "TLR4 is an important mediator of innate immune response activation following infection with S. Typhimurium via recognition of lipopolysaccharide (LPS), and we observed that TLR4 was highly upregulated in the ileal and colonic tissue of infected animals at 4 dpi." (PMID 36365008, 2022). "As reported, these receptors, in synergy with TLR4, mobilize HSPCs during infection, promoting their egress from BM into PB and subsequently their homing into the spleen, which plays an important role as an extramedullary place of hematopoiesis during stress situations." (PMID 34853440, 2022). "Moreover, endocytosed lumican colocalizes with TLR4 and LPS and promotes endosomal induction of type I interferons, in explaining the effects of the extracellular matrix on infection and immunity." (PMID 35844488, 2022). "These compatibilities between the NT-Ab binding sites of virus proteins and cellular receptor binding sites (TLR4/MD-2 complexes) may explain why palivizumab prevents the infection to host cells." (PMID 36366480, 2022). "In conclusion, our findings characterizing the kinetics of inflammatory markers may constitute a step toward understanding parts of the TLR4-mediated immune response during an infection." (PMID 35861876, 2022). "Toll-like receptor 4, a member of toll-like receptor family, belongs to the family of pattern recognition receptor that plays a key role in the activation of innate immune response participating in response to a wide range of pathogen infection." (PMID 35968000, 2022). "High MR expression and low TLR4 expression were observed in both infections." (PMID 35628694, 2022). "After infection for 4 h, relative expression levels of TLR4 in HBMEC increased 8.30 fold." (PMID 34163451, 2021). "Calprotectin binds to TLR4 which can explain inflammation and infection." (PMID 34458672, 2021). "However, greater parasite multiplication and higher TLR2 and TLR4 expression were seen in monocytes from DL patients compared to CL following infection with DL isolates." (PMID 34568099, 2021). "TLR4 allows translocation and activation of the transcription factor NF-ĸB, which stimulates synthesis and secretion of cytokines (IL-6, TNFα) at the site of the infection, which will propagate the immune response." (PMID 33801785, 2021). "LPS tolerance, in which cells become less responsive to LPS, is observed in Goto-Kakizaki rats (a T2D model), and mediated by impaired Toll-like-receptor 4 (TLR4) signalling which may have profound consequences on immune responses to infection." (PMID 34149714, 2021). "Nevertheless, Leishmania donovani-infection subverts both these pathways of TLR4 activation." (PMID 33763070, 2021). "Hence, a finer knowledge of TLR4-mediated signaling is key to find helpful targets for the management of infections and inflammatory diseases." (PMID 34757442, 2021). "In addition, the induction of BBB permeability and upregulation of MMP-9 during CNS VEEV TC-83 infection are dependent on TLR4." (PMID 33487119, 2021). "Here, TLR4-defective C3H/HeJ mice infected with C. perfringens showed a remarkable decrease in survival rate, an increase in viable bacterial counts, and accelerated destruction of myofibrils at the infection site compared with wild-type C3H/HeN mice." (PMID 33763386, 2021). "At the higher temperature of 37°C associated with mammalian infection, TLR2 was primarily activated with concurrent suppression of TLR4 activation that coincided with the biosynthesis of tetra- or penta-acylated modified forms of lipid A as previously reported." (PMID 34888257, 2021).
infection (continued). "The present study endeavored to evaluate whether TLR2 and TLR4 neutralization leads to impaired monocyte infection, consequently modulating the inflammatory response observed in American tegumentary leishmaniasis (ATL) caused by L. braziliensis." (PMID 34691019, 2021). "Additionally, TLR2 and TLR4 expression was higher in DL monocytes compared to CL monocytes after infection with a DL isolate (p<0.01 and p<0.05)." (PMID 34568099, 2021). "The TLR4/NF-κB signal is often activated in pathogen infection." (PMID 34093546, 2021). "Accordingly, here, we attempted to address whether MyD88- and TRIF-mediated TLR4-signaling is dependent either on Neu1 or Siglec-E or both together through their action on the sialic acids of TLR4 during this infection." (PMID 33763070, 2021). "As a classic PRR, TLR4 might act as a key bridge molecule between the infection of oncogenic pathogens (such as F. nucleatum and Salmonella) and the colonic inflammatory process." (PMID 34479599, 2021). "A possible explanation may be that TLR4 is located on the plasma cell surface to form the first line to sense pathogen and counteract infection." (PMID 34621265, 2021). "TIGF infection with F. nucleatum induced IL-6 and IL-8 secretion in TIGFs, albeit to a lesser extent than in primary cells, indicating that TIGFs are capable of responding to infection through TLR4, but this response is diminished compared to primary cells in the absence of TLR2." (PMID 34031466, 2021). "In contrast to our results, the upregulation of TLR4 expression may be related to modulation of AD development as well as protection of infection." (PMID 34691014, 2021). "Similarly, Ad-TLR4 infection in HepG2 cells offset the crippling effect of BRG1 depletion by maintaining SREBP1a expression." (PMID 33816466, 2021). "We pre-treated RAW cells with TLR4-IN-C34 prior to infection with DSV." (PMID 34336718, 2021). "Due to their LPS content, they all have the ability to activate TLR4, although their infection characteristics (such as where and how they infect) raise questions as to what cells would, and could, recognise them." (PMID 33446670, 2021). "Mutations in mouse and human TLR4 were found to be associated with hyporesponsiveness to LPS and to confer an increased risk of infection with Gram-negative bacteria." (PMID 34482448, 2021). "Regarding protective immunity, NMII infection induces toll-like receptor 4-independent dendritic cell maturation with high IL-12 and TNF production, implying that NMII might activate dendritic cell-mediated T-cell response in the host." (PMID 34795669, 2021). "Moreover, a reciprocal interplay between Neu1 and siglec-E differentially regulates MyD88- and TRIF-pathways through sialic acids on TLR4 as their common substrate during infection." (PMID 33763070, 2021). "Thus our data indicate TLR4 is ubiquitinated and degraded during infection which is inhibited under Neu1 overexpressed or siglec-E silenced infected conditions." (PMID 33763070, 2021). "Additionally, the top predicted transcriptional regulators (P < .01) at 2 h post-infection of the pre-treated cells were dextran sulfate, TLR4, kinase EIF2AK3, FCGR2A, and LEP." (PMID 33382951, 2021). "There was a differential regulation of TLR4-activation pathways during this infection." (PMID 33763070, 2021). "The hypervariable region of TLR4, where MD-2 complexes with TLR4, has only 48% similarity between humans and mice, which again might lead to differences in how the host responds to infections." (PMID 34123879, 2021). "Alternatively, the kinetics of infection may have been altered between flight and ground cultures, where TLR4 expression in the infected flight cultures may have occurred outside of our analysis time point." (PMID 33750813, 2021). "TLR4-MyD88/Mal-NF-kB axis is involved in infection of HSV-2 in human cervical epithelial cells." (PMID 34630083, 2021).